HSP90AB4P (heat shock protein 90 alpha family class B member 4, pseudogene)
Description:
Putative molecular chaperone that may promote the maturation, structural maintenance and proper regulation of specific target proteins.
Gene: Processed pseudogene on chromosome 15 (58,691,106 to 58,693,125, reverse strand). Ensembl gene ENSG00000282100.
Subcellular location: Cytoplasm